PRAME (PRAME nuclear receptor transcriptional regulator)
Diseases named in the same sentence as PRAME in open-access papers (continued):
Sharing a sentence is not in itself a finding about the gene and the disease.
breast carcinoma (continued). "In solid malignancies, including hepatocellular carcinoma, uveal melanoma, osteosarcoma, bladder cancer, and breast carcinoma, high PRAME expression correlates with advanced-stage disease and poor survival, whereas in pediatric acute leukemia, PRAME overexpression was found to predict good outcome." (PMID 33381588, 2020). "Moreover, PRAME expression correlates with higher tumour grade and poorer prognosis in neuroblastoma, urothelial carcinoma, osteosarcoma, head and neck carcinoma, breast cancer, liposarcoma, chronic myeloid leukaemia, and lymphomas." (PMID 32704057, 2020). "We evaluated the expression of the tumor-associated antigen PReferentially Antigen expressed in MElanoma (PRAME) as a prognostic biomarker in breast cancer and explored its role in cell migration and invasion, key hallmarks of progressive and metastatic disease." (PMID 30602372, 2019). "We found an increased expression of PRAME in cancer tissues compared to the corresponding normal tissues for the most common cancer types among women worldwide (breast cancer, colorectal cancer, lung cancer) in addition to its well-known upregulation in melanoma." (PMID 30602372, 2019). "In addition to HER2 and PRAME which are expressed in 17% and 53% of breast cancers, respectively, CT antigens have also been targets for vaccine trials and are desirable antigens due to their restricted expression pattern." (PMID 28837000, 2014). "The function of PRAME in breast cancer and other cancers in which it is expressed is still elusive." (PMID 18648365, 2008). "Moreover, in both primary breast cancer and uveal melanoma, higher PRAME expression levels correlate with an increased rate of distant metastases and may promote epithelial-to-mesenchymal transition during tumor invasion." (PMID 39659431, 2024). "Moreover, we found that PRAME overexpression in breast cancer cells dampens peripheral blood lymphocyte activation and cancer cell killing, concomitant with decreased levels of soluble pro‐inflammatory immune mediators and increased immune checkpoint expression." (PMID 34612587, 2021). "It is noteworthy that PRAME has previously been confirmed to play a role in promoting EMT in ESCC and breast cancer, and it is correlated with malignant behavior of the proliferation, migration, and invasion." (PMID 36910848, 2023). "A total of 137 breast cancer tissue specimens including 51 triple-negative breast cancer (TNBC) were assessed for MAGE-A4, MAGEA1, NY-ESO-1, KK-LC-1 and PRAME expression by immunohistochemistry." (PMID 37610673, 2023). "Several clinical trials are currently being conducted to evaluate the effectiveness of CTAs, such as NY-ESO-1, MAGE, MSLN, PRAME, PSCA, ROR2 and WT1, as treatment targets in breast cancers and other solid tumours." (PMID 34359776, 2021). "At the same time, higher expression of 4 important genes (NMU, COL2A1, PRAME, and TTYH1) that contribute to higher breast cancer lung metastasis was observed in the tumors from Black women compared to the tumors from white women with an adjusted p-value of 0.000664734 (one-way ANOVA)." (PMID 36702853, 2023). "MAGE-A1 and PRAME were non-significantly different between the two groups with 2.92% and 27.01% in breast cancer, respectively." (PMID 37610673, 2023). "We conclude that PRAME expression is a prognostic marker for clinical outcome of breast cancer, independent of traditional clinicopathological markers." (PMID 18648365, 2008). "The PReferentially expressed Antigen in Melanoma (PRAME) is a testis-selective cancer testis antigen (CTA) with restricted expression in somatic tissues and preferentially expressed in variety of cancers, including NSCLC, metastatic melanoma, breast cancer, and neuroblastoma." (PMID 35632496, 2022). "Similarly, we observed lower RARα levels in tumours having high PRAME expression, suggesting that PRAME may also not act through RARα in breast cancer." (PMID 18648365, 2008).
uveal melanoma (26 papers, 2016 to 2026). A melanoma derived from melanocytes of the uveal tract. "In uveal melanoma, which originates in the uvea and differs genetically from cutaneous melanoma, PRAME overexpression is linked to poor prognosis and increased liver metastasis risk." (PMID 40868240, 2025). "The overexpression of PRAME in uveal melanoma has been linked to a worse prognosis and an increased risk of metastasis, particularly in the liver." (PMID 38338862, 2024). "In uveal and conjunctival lesions, PRAME overexpression in uveal melanoma correlates with an increased risk of metastasis, while its role in conjunctival melanoma is less clear, but suggests potential as a biomarker." (PMID 38338862, 2024). "A recent study showed that the expression of the oncogene PRAME in a group of uveal melanoma patients allowed the identification of a group of class 1 patients with intermediate metastatic risk, and these uveal melanomas often harbor SF3B1 mutations." (PMID 29156643, 2017). "We previously reported that PRAME mRNA expression is a significant risk factor for metastasis in Class 1 uveal melanomas, and we developed a general method for establishing a PRAME+ threshold in various datasets." (PMID 27486988, 2016). "We previously showed that PRAME expression was associated with increased metastatic risk in Class 1 uveal melanomas." (PMID 27486988, 2016). "PRAME is aberrantly hypomethylated and activated in Class 1 and Class 2 uveal melanomas and is associated with increased metastatic risk in both classes." (PMID 27486988, 2016). "Moreover, analysing uveal melanoma drivers of mutations, PRAME+ status was found to be directly associated with SF3B1 alterations, while it was inversely associated with EIF1AX changes in class 1 tumours." (PMID 31109147, 2019). "We previously identified PRAME as a biomarker for metastatic risk in Class 1 uveal melanomas." (PMID 27486988, 2016). "The common association of PRAME expression and isochromosome formation on chromosomes 6 and 8 is of interest and may provide new insight into uveal melanoma tumorigenesis." (PMID 27486988, 2016). "A notable example is a clinical trial assessing the safety and antitumor activity of BPX-701, a TCR-engineered autologous T-cell product targeting PRAME in patients with metastatic uveal melanoma." (PMID 40868240, 2025). "PRAME expression extends to various other cancer types, including uveal melanoma, non-small cell lung cancer (NSCLC), kidney cancer, bladder cancer, head and neck squamous cell carcinoma (HNSCC), and esophageal carcinoma." (PMID 39204391, 2024). "While PRAME was found to be related with metastasis in uveal melanoma, little has been reported about the prognostic value of PRAME expression in cutaneous melanoma." (PMID 35484605, 2022). "Currently, other biological prognostic markers are explored with the expression of PRAME or autophagy related proteins in primary uveal melanoma specimens." (PMID 34830903, 2021). "From a therapeutic perspective, PRAME has been studied as an attractive target for antigen-specific immunization by adoptive T-cell therapy in some tumours, such as uveal melanoma and non-small cell lung cancer." (PMID 32704057, 2020). "PRAME had been reported as an independent marker for metastasis in uveal melanoma, indicating the value as a marker in the process of PM31." (PMID 31570735, 2019). "In summary, we have provided a threshold for PRAME+ expression from qPCR data for primary uveal melanomas across a wide spectrum of tumor sizes and in both tumor classes representative of actual clinical practice." (PMID 27486988, 2016). "The purpose of the present study was to study PRAME expression in a much larger number of Class 1 and, for the first time, in Class 2 uveal melanomas spanning the true range of tumor sizes encountered in clinical practice." (PMID 27486988, 2016).
uveal melanoma (continued). "In the present study that included a much larger number of samples that better represented the full spectrum of uveal melanomas, we observed a highly significant correlation between PRAME+ status and “1B” status." (PMID 27486988, 2016). "Testes is the only normal adult tissue that expresses PRAME mRNA at appreciable levels, which strongly suggests that the expression of PRAME in uveal melanoma is anomalous." (PMID 27486988, 2016). "Furthermore, due to the nature of the cancer/testis antigens of PRAME, this protein has been recognized as a potential target for immunotherapy in patients with some types of malignant tumor, such as uveal malignant melanoma and non-small-cell lung cancer." (PMID 38132219, 2023). "Successful efforts to target the intrinsically disordered-based proteins of PRAME may reduce rates of metastasis and poor outcomes in Class 1 uveal melanomas." (PMID 37626310, 2023). "In addition, in vitro HLA-A*02-restricted, PRAME-specific T cells were able to recognize and react against PRAME-positive uveal melanoma cell lines, suggesting a potential role for PRAME-directed immunotherapy." (PMID 35267523, 2022). "Interestingly, the PRAME gene, which is an independent biomarker of uveal melanoma metastasis, was also significant expressed in the high-risk group." (PMID 33193373, 2020). "Unexpectedly, PRAME, which acts as an independent biomarker in uveal melanoma metastasis, was also significantly expressed in the high-risk group, indicating that PRAME may also be a biomarker in CM." (PMID 33193373, 2020). "PRAME is a cancer metastasis gene in uveal melanoma and in lung cancer." (PMID 28678795, 2017). "PRAME is a cancer metastasis gene involved in uveal melanoma and lung cancer." (PMID 28678795, 2017). "Our finding that PRAME becomes aberrantly hypomethylated and transcriptionally activated during uveal melanoma progression is similar to findings in other cancers and may have therapeutic implications." (PMID 27486988, 2016). "Recent advances seen with tebentafusp in metastatic uveal melanoma and tarlatamab in small-cell lung cancer have validated the approach and driven a rapidly expanding pipeline targeting other tumor associated antigens such as STEAP1, MUC16, and PRAME among others." (PMID 41964902, 2026). "Thus, PRAME may be a potential candidate for direct immunotherapy for patients with uveal malignant melanoma expressing PRAME." (PMID 38132219, 2023). "Finally, we showed that specific CpG sites around the PRAME promoter are differentially hypomethylated in PRAME+ tumors, suggesting that the aberrant transcriptional activation of PRAME in uveal melanoma is the result of epigenetic reprogramming during tumor progression." (PMID 27486988, 2016). "Consequently, we hypothesized that PRAME may become aberrantly activated in uveal melanoma by hypomethylation of the promoter region." (PMID 27486988, 2016).
acute myeloid leukemia (24 papers, 2012 to 2026). Acute myeloid leukemia (AML) is a group of neoplasms arising from precursor cells committed to the myeloid cell-line differentiation. "Several studies suggest that DNA hypomethylation is associated with up-regulation of PRAME expression in acute myelogenous leukemia (AML), MDS, and ovarian cancer." (PMID 39091741, 2024). "In contrast, PRAME expression was downregulated in acute myeloid leukemia, where it has been reported to be associated with a more favorable outcome." (PMID 30602372, 2019). "Furthermore, PRAME-specific T cells were associated with long-term survival of patients with acute myeloid leukemia (AML) after allogeneic stem cell transplantation." (PMID 39858024, 2025). "Recent studies have highlighted the clinical significance of PRAME expression in acute myeloid leukemia (AML)." (PMID 40868240, 2025). "Vaccination with DCs electroporated with mRNA encoding WT1 (NCT00965224) or WT1, PRAME, and CMVpp65 (NCT01734304) or CT7, MAGE-A3, and WT1 mRNA (NCT01995708) or WT1/PRAME (NCT02405338) mRNA was tested in acute myeloid leukemia (AML)." (PMID 36839944, 2023). "In acute myeloid leukemia cells, the overexpression of PRAME correlates with the decreased expression of Hsp27 (heat shock protein 27), S100A4, and p21 at the transcription levels." (PMID 38132219, 2023). "PRAME is an intracellular cancer and testis antigen highly expressed in acute myeloid leukemia blasts and normal reproductive tissues." (PMID 37345050, 2023). "Recently, generation of cytotoxic T cells targeting PRAME antigens for the treatment of acute myeloid leukemia, chronic myeloid leukemia, and medulloblastoma has been reported." (PMID 35380993, 2022). "Some studies have described a favorable prognosis with PRAME overexpression in both acute myeloid and lymphoblastic leukemia in pediatric patients as well as acute myeloid leukemia in adults." (PMID 35076507, 2021). "PRAME expression was further enhanced in acute myeloid leukemia cell lines after combined treatment with chidamide and DNA demethylating agent decitabine." (PMID 23940586, 2013). "As one of the best known cancer testis antigens, PRAME is overexpressed exclusively in germ line tissues such as the testis as well as in a variety of solid and hematological malignant cells including acute myeloid leukemia." (PMID 23940586, 2013). "In this study, we observed remarkably increased PRAME mRNA expression in human acute myeloid leukemia cell lines and primary acute myeloid leukemia cells after treatment with a novel subtype-selective histone deacetylase inhibitor chidamide in vitro." (PMID 23940586, 2013). "The PRAME gene was expressed in 38.2% of all 34 patients, in 40.7% of the patients with acute myelogenous leukemia (AML, n=27), and in 28.6% of the patients with acute lymphoblastic leukemia (ALL, n=7), but was not expressed in the healthy volunteers." (PMID 23691459, 2012). "PRAME is prominently expressed in hematopoietic malignancies as well, with notable prevalence in conditions such as acute myeloid leukemia (AML) (40–60%), acute lymphoblastic leukemia (ALL) (20–40%), myeloma (20–50% of cases), and chronic myeloid leukemia (CML) (30–40%)." (PMID 39204391, 2024). "In hematological malignancies, PRAME has displayed particularly high expression in Acute Myeloid Leukemia (AML), Acute Lymphoid Leukemia (ALL) and Chronic Myeloid Leukemia (CML) in blast crisis." (PMID 29029482, 2017). "Preferentially Expressed Antigen in Melanoma (PRAME) may be well suited for TCR-T therapy of acute myeloid leukemia (AML) and myelodysplastic syndrome (MDS) through its broad overexpression in leukemic blasts of myeloid origin." (PMID 41008812, 2025). "As revealed by the in vitro study in human acute myeloid leukemia cells, a selective HDAC inhibitor chidamide can upregulate PRAME mRNA expression." (PMID 36910848, 2023).
acute myeloid leukemia (continued). "We found several peptides from proteins known to be dysregulated in DIPG, including IL13Rα2, PRAME, and MAGE, which are also known to generate strong, anti-tumor responses in neuroblastoma and acute myeloid leukemia." (PMID 37637064, 2023). "Another multi-TAA peptide vaccine approach directed against PRAME, NY-ESO-1, MAGE-A3, and WT-1 in combination with 5′-aza-2′-deoxycytidine is currently in phase I trial in patients with myelodysplastic syndrome and acute myeloid leukemia (NCT02750995)." (PMID 31311081, 2019).
metastatic melanoma (24 papers, 2010 to 2025). A melanoma that has spread from its primary site to another anatomic site. "Among the 12 metastatic melanoma cases, 8 exhibited a score of +4, 2 had a score of +3, and 2 showed a score of +2 for PRAME expression." (PMID 41153267, 2025). "They reported PRAME expression in 99% of mucosal melanomas and 87% of metastatic melanomas, with diffuse positivity in 85% and 75% of cases, respectively." (PMID 41153267, 2025). "In our case, PRAME negativity strongly favored a benign diagnosis, and this finding was critical in excluding metastatic melanoma." (PMID 40984891, 2025). "In one study, PRAME was found to be diffusely positive in 92% of metastatic melanomas and in 92% of primary cutaneous melanomas, excluding desmoplastic variants." (PMID 40868240, 2025). "In fact, in one of the first studies conducted on this topic, the authors presented their findings regarding the immunoexpression of PRAME in 400 melanocytic tumors, including 155 primary and 100 metastatic melanomas, and 145 melanocytic nevi." (PMID 35328098, 2022). "One study showed that around 87% of metastatic melanomas expressed PRAME in a diffuse homogenous pattern, with an additional 5% of cases (total of 92% of cases) showing at least focal immunoreactivity." (PMID 35565234, 2022). "We observed PRAME expression in 84.6% of patients, which is in the range reported in the literature for metastatic melanoma." (PMID 27843625, 2016). "While PRAME is absent or expressed at very low levels in most normal tissues tested, high levels of PRAME mRNAs are encountered in malignant cells, including the vast majority of primary and metastatic melanomas (88% and 95% respectively)." (PMID 20799951, 2010). "Several studies have demonstrated high PRAME expression in metastatic melanoma." (PMID 41153267, 2025). "In our cohort, PRAME expression was detected in all metastatic melanoma cases." (PMID 41153267, 2025). "PRAME expression was retained in metastatic melanoma and lung tumor lesions." (PMID 39659431, 2024). "Indeed, SCD5 overexpression in metastatic melanoma was sufficient to reduce PRAME, in turn activating MITF and SOX9, which were further increased by ATRA." (PMID 29484133, 2018). "While initial interpretation favored metastatic melanoma, further IHC workup demonstrated low proliferative activity (Ki-67 <1%), diffuse p16 positivity, and negativity for both HMB-45 and PRAME." (PMID 40984891, 2025). "They demonstrated that PRAME expression was positive in the majority of both primary and metastatic melanoma (83.2% and 87%, respectively) and negative in the majority of benign melanocytic nevi (86.4%)." (PMID 40227827, 2025). "Normal healthy tissues are not known to express PRAME except for the testis, ovary, placenta, adrenals, and endometrium, thus, its expression in melanocytes is a strong indicator of metastatic melanoma." (PMID 35565234, 2022). "Further tumor immunohistochemistry revealed extensive neuroendocrine differentiation with CD56, synaptophysin, and INSM1, as well as strong immunoreactivity for melanocyte markers including SOX10, S100, PRAME, and MITF, consistent with metastatic melanoma with neuroendocrine differentiation." (PMID 34926265, 2021). "We observed negative PRAME staining and positive 5hmC staining (PRAME−/5hmChigh) in benign nevi, and the opposite pattern of low 5hmC and high PRAME (PRAME+/5hmClow) in MIS, primary and metastatic melanomas." (PMID 39091741, 2024).